STAG3 (STAG3 cohesin complex component)
Diseases named in the same sentence as STAG3 in open-access papers (continued):
Sharing a sentence is not in itself a finding about the gene and the disease.
cancer (13 papers, 2006 to 2025). A tumor composed of atypical neoplastic, often pleomorphic cells that invade other tissues. "Further investigations are warranted to understand how STAG3 affects carcinogenesis in HPV-associated cancers." (PMID 34830845, 2021). "And GSEA revealed AREG, CAV1 and STAG3 were associated with dysregulated pathways in cancer." (PMID 33712015, 2021). "STAG3 is found in germ cells and certain cancer cell lines, and only recently it was also observed in mouse embryonic stem cells." (PMID 41492387, 2025). "This indicates that the potential misregulation of somatic cohesin by STAG3 is a common event in cancers, while the expression of full meiotic cohesin, to include SMC1β and RAD21L, appears to be rare." (PMID 25408876, 2013). "STAG3 activation is found practically in every dataset in Oncomine (September 2012 release), including all types of cancers, with some of datasets showing over 50% of samples overexpressing STAG3 over 2-fold." (PMID 25408876, 2013). "RAD21L, SMC1β and STAG3 subunits have drastically distinct patterns of activation/overexpression in cancers, however." (PMID 25408876, 2013). "COSMIC database of cancer genomic data contains 15 examples of mutations in RAD21L, some of them reoccurring, 83 mutations in SMC1β, and 88 in STAG3." (PMID 25408876, 2013). "However, reactivation of the cancer testis antigen STAG3 has been reported in cancers." (PMID 35251135, 2022). "However, STAG3 overexpression is also a common event in various cancers." (PMID 34830845, 2021). "The role of AREG, STAG3, CAV1 and C19orf57 in cancer were analyzed through Gene set enrichment analysis (GSEA)." (PMID 33712015, 2021). "STAG3 overexpression has been previously reported for cancer cells but not for normal somatic cells." (PMID 41492387, 2025). "Other genes, including DMC1, STAG3 and REC8, allow somatic cancer cells to escape radiation-induced cell death without directly affecting the intracellular DNA repair pathways." (PMID 35251135, 2022).
genetic disorders (2 papers, 2017 to 2021). "Due to the large size of STAG3 (34 exons) and to eventually disclose pathogenic variants in other genes a NGS platform including 5227 genes (Agilent SureSelect Custom Constitutional Panel 17) involved in human genetic disorders (Clinical Exome) was used to identify the causative molecular defect." (PMID 34828315, 2021).
STAG3 also shares sentences with these, for which no sentence is quoted: infection (4 papers); Ovarian Insufficiency (2); Anxiety (1); Bardet-Biedl syndrome (1); bipolar disorder (1); bladder carcinoma (1); cognitive decline (1); Colon Cancer (1); diabetes (1); HIV-1 infection (1); Hodgkins lymphoma (1); mastitis (1); Sepsis (1); Spastic tetraplegia (1); testicular cancer (1).